RNU6-99P (RNA, U6 small nuclear 99, pseudogene)
Gene: Small nuclear RNA gene on chromosome 11 (39,261,107 to 39,261,213, forward strand). Ensembl gene ENSG00000201591.
Homologues: Orthologues: chimpanzee U6 (98% identical), macaque U6 (87% identical). Paralogues in human: RNU6-1131P (84% identical), RNU6-1152P (83% identical), RNU6-1060P (82% identical), RNU6-1270P (82% identical), RNU6-536P (82% identical), RNU6-1011P (81% identical), RNU6-106P (81% identical), RNU6-116P (81% identical), RNU6-1181P (81% identical), RNU6-16P (81% identical), RNU6-187P (81% identical), RNU6-633P (81% identical), and 1288 more.